CD1D (CD1d molecule)
Diseases named in the same sentence as CD1D in open-access papers (continued):
Sharing a sentence is not in itself a finding about the gene and the disease.
tumor (continued). "Consequently, in several tumor models, CD1d−/− mice falling short on both kinds of NKT cells showed an antitumor or antimetastatic effect at one level or another." (PMID 37152373, 2023). "Whilst it is likely that alteration of CD1d expression will in turn enable tumour escape from NKT cell-mediated immunosurveillance, it is also possible that altered expression of CD1d contributes to metabolic alterations in tumour cells by regulating CD36 functions." (PMID 36344546, 2022). "Our proposed vaccine, NKT ligand-loaded CD1d+ cells carrying the tumor antigens that target dendritic cells and induces activation of innate immunity and antigen-specific CD4+ and CD8+ T cell responses, named artificial adjuvant vector cells (aAVC), should be efficacious." (PMID 35269735, 2022). "Type I NKT cells can have direct oncolytic function on CD1d-expressing tumor cells." (PMID 36052072, 2022). "The immune reaction is triggered by expression of ‘stress’ induced tumour haptens, loss of inhibitory molecules on the tumour and expression of tumour antigens, in context of MHC class I and II molecules (Th‐1 and CTLs respectively) or CD1D (NKT cells)." (PMID 35445563, 2022). "Moreover, iNKT cells themselves show strong anti-tumor effects in tumor models via the CD1d-mediated killing of CD1d-positive tumor cells and immunosuppressive TAMs and MDSCs." (PMID 35563634, 2022). "iNKT cells exert anti-tumor effector cell activities by producing several Th1 cytokines, i.e. IFNγ, TNFα, and by eliminating CD1d-expressing tumor cells, thus they represent a potential intriguing therapeutic cellular tool against cancer development and metastasis." (PMID 36338516, 2022). "The CD1D molecules may stimulate anti-tumor immune responses by presenting tumor-derived lipid and glycolipid antigens to T cells and NKT cells." (PMID 35620271, 2022). "In a subcutaneous CT26 tumor model, suppressing Treg functions with anti-CD25 treatment induced the rejection of tumors in both wild-type mice and type I and II NKT cell-deficient CD1d KO mice." (PMID 34208864, 2021). "Previous studies have shown that the therapeutic administration of CD1d-expressing DCs pulsed with α-GalCer (forming α-GalCer-CD1d complex) inhibited tumor growth and metastasis and prolonged the survival of tumor-bearing hosts compared with free α-GalCer administration." (PMID 35008335, 2021). "Therefore, to increase the iNKT cell targeting of tumors, CD1d-antibody fusion proteins that direct iNKT cell lysis towards the tumor have been examined." (PMID 34680322, 2021). "Coupled with the downregulation of CD1d on tumor cells, treatment efficacy can be limited." (PMID 34680322, 2021). "In addition to the analysis of infiltrating lymphocytes, it was important to analyze the tumor samples regarding their CD1d expression for potential antigen presentation." (PMID 32973759, 2020). "Moreover, iNKT cells have the ability to kill CD1d-expressing tumor cells directly via the perforin/granzyme B, Fas-Fas ligand system and tumor necrosis factor-α-related apoptosis-inducing ligand (TRAIL)." (PMID 32973759, 2020). "In addition, optimal iNKT cell-mediated, anti-tumor responses generally require tumor cell expression of CD1d." (PMID 32560408, 2020). "Combined with our findings, we presumed that Sca-1−CD62L+ CD1d-independent NKT cells might affect the immune tumor microenvironment through the secretion of IFN-γ." (PMID 33173202, 2020). "The anti-tumor activity of CD1d-restricted lipid targeted αβ-TCR invariant natural killer T cells (iNKT) cells has already been established in preclinical model systems, and is also being investigated clinically, for example for hepatocellular carcinoma (NCT04011033)." (PMID 32570906, 2020). "Activated type I NKT-cells are capable of killing CD1d+ tumor cells in a CD1d-dependent manner." (PMID 32582698, 2020). "However, many tumors evade or dampen iNKT cell anti-tumor response by downregulating CD1d or by actively suppressing iNKT cell functions." (PMID 32708464, 2020).
tumor (continued). "However, transformed cells often down-regulate CD1d expression, which results in a reduction of iNKT cell anti-tumor functions." (PMID 32560408, 2020). "Whether Vδ1 T cells may recognize specific lipid antigens presented by CD1d on the surface of tumor cells deserves further investigation." (PMID 32413966, 2020). "Furthermore, a strong expression of CD1d molecules by tumor cells was observed in both samples, which function as a lipid antigen-presenting structure." (PMID 32973759, 2020). "However, by 1998, studies using knockout mice had concluded that α-GalCer's anti-tumor properties were mediated by CD1d-restricted iNKT cells." (PMID 31244823, 2019). "In fact, the level of CD1d expression on tumor cells dictates NKT-mediated cytotoxicity." (PMID 31143179, 2019). "Furthermore, the immunohistological analysis of spleen and tumor tissues showed the presence of α-GalCer-CD1d tetramer+ NKT cells." (PMID 31387637, 2019). "Besides their immunomodulatory functions, iNKT cells can directly recognize and kill CD1d+ tumor cells." (PMID 31569599, 2019). "Therefore, CD1d expression on tumor cells can be a positive biomarker for future iNKT cell therapies in clinics, as suggested by another report." (PMID 31244823, 2019). "We can hypothesize that accumulation of tumor specific lipids in the tumor microenvironment can affect the expression of CD1d on both tumor cells and DCs, thereby suppressing their immunogenicity and facilitating eventual immune evasion." (PMID 31620124, 2019). "Moreover, CD1D-restricted NKT cells have a crucial role in tumor rejection and immune regulation and are dependent on the regulatory relation between LEF1 and the CD1D gene." (PMID 31684152, 2019). "Since most CD11c+ cells would also express CD1d molecules, those cells in the tumor microenvironment might activate iNKT cells either in the tumor itself or in the draining lymph node." (PMID 31690657, 2019). "Activated NKT cells are able to kill tumor cells directly in a CD1d-dependent manner." (PMID 29535734, 2018). "The first is that iNKT cells directly recognize and kill CD1d-expressing tumor cells." (PMID 29559971, 2018). "This could be by direct CD1d targeting either on the surface of the tumor cell or a bystander tumor-promoting myeloid cell, or via removing immunosuppression by killing CD1d + TAMs." (PMID 29559971, 2018). "The potential of this approach has been demonstrated using a bispecific molecule generated by genetic fusion of a single chain variable fragment (scFv) targeted to a specific tumor peptide and CD1d, which can be loaded with specific glycolipids to allow iNKT cell activation." (PMID 30013569, 2018). "The development of antagonistic Ags for type II NKT cells that have higher affinity for CD1d than tumor Ags may enable blocking the signaling between tumor lipid Ags and type II NKT cells." (PMID 29520281, 2018). "The factors that determine whether NKT cells promote or suppress tumor immunity are not well understood, but it is possible that NKT cell activation by CD1d-expressing tumor cells will favor immunosuppressive functions." (PMID 30210505, 2018). "TH2- and Treg-like NKT cell subsets might still be able to kill tumor cells, either via CD1d-dependent or CD1d-independent mechanisms." (PMID 29535734, 2018). "Moreover, imaging techniques will help demonstrate that oligomerization of CD1d-antitumor proteins on the tumor cell likely optimize the formation of an immunological synapse with the iNKT cell." (PMID 29163493, 2017). "On other hand, the lack of such drawbacks in glycolipid analogues containing phenyl groups in the lipid tails of α-GalCer coupled with the greater binding avidity and stability of CD1d-glycolipid complex for iNKT T-cell receptor, account for their superior anti-cancer efficacy in tumor bearing mice." (PMID 28335781, 2017).
tumor (continued). "Finally, combination therapy using monoclonal Abs targeting CD1d alone or in combination with tumor cell death inducing and immunomodulating mAbs has emerged as promising immunotherapeutic candidate against CD1d-negative cancers." (PMID 29018445, 2017). "Finally, human embryonic stem cell-derived DCs genetically engineered to express CD1d can prime CD8+ T cells against tumor antigens." (PMID 28798749, 2017). "UPR activation might lead to sorting of self-lipid antigens onto CD1d complexes on CD1d+ tumor or surrounding immune cells—which in conjunction with inflammatory cytokines might become immunogenic." (PMID 29326711, 2017). "In this review, we examine the critical role of iNKT cells in antitumor responses from two perspectives: (i) how iNKT cells potentiate antitumor immunity and (ii) how CD1d+ tumor cells may modulate their own expression of CD1d molecules." (PMID 29326711, 2017). "CD1d is generally expressed on most hematopoietic cells, e.g., DCs, B cells, T cells, and macrophages, and on some non-hematopoietic cells, e.g., intestinal epithelium and hepatocytes, including multiple tumor types." (PMID 28824620, 2017). "Tumor-derived factors can also inhibit trans-CD1d-dependent antigen presentation." (PMID 29326711, 2017). "In the large proportion of cases where solid tumors are CD1d−, tumor-infiltrating CD1d+ myeloid populations might activate iNKT cells either within the tumor or in distal lymphoid tissues enriched in iNKT cells." (PMID 29326711, 2017). "The analysis of peripheral lymphoid organs and tumor tissue revealed (i) localization of CD1d-antitumor proteins at the tumor site, (ii) recruitment of iNKT, NK, and T cells at the tumor, (iii) sustained activation of iNKT cells, and (iv) adjuvant effect on CD8 T cell priming." (PMID 29163493, 2017). "Besides these examples, there is little information available about the contribution of CD1d-presented lipids that are cancer specific or upregulated in cancer to activation of NKT cells in tumor immunity." (PMID 29375569, 2017). "CD1d is expressed by a multitude of cell types but is specific for presentation of glycolipid antigens to iNKT cells, a cell population previously shown to be an important player in the host’s anti-tumor defense." (PMID 28212574, 2017). "However, mice containing human CD1d are protected from tumor metastasis via α-GalCer treatment, despite having iNKT cell frequencies comparable to humans." (PMID 27471636, 2016). "This strengthens the hypothesis that high CD1d expression levels on tumor cells correlate with lower metastasis rates." (PMID 26895468, 2016). "Finally, to evaluate the role of the innate IR in P2Et-mediated anti-tumor activity, we performed NK cell depletion, and also tested the P2Et fraction in CD1d KO mice to evaluate a possible role of type 1 and type 2 natural killer T (NKT) cells." (PMID 27253407, 2016). "Finally, adoptive transfer of small numbers of purified iNKT cells into lymphocyte-deficient NOD-Scid-IL2rγ−/− (NSG) mice was sufficient to protect mice from challenge with a CD1d+ tumor." (PMID 26543874, 2015). "Targeting CD1d on both the tumor cells and the supporting stromal cells could be an effective approach." (PMID 26052329, 2015). "Despite the majority of studies implicating iNKT cells as having an antitumor role, a limited number of studies also implicate iNKT cells as suppressing antitumor responses, but these paradoxic responses may be related to the level of tumor CD1d expression." (PMID 26543874, 2015). "Whether the percentage of CD1d-presented α-anomeric glycolipids is altered in tumor tissues represents an interesting question that deserves further future investigation." (PMID 26543874, 2015).
tumor (continued). "Next, anti-CD1d mAb was given to 4T1 tumor-bearing WT mice starting on day 3 post-tumor inoculation and tumors and dLN analyzed at day 13, a time when tumors are irradiated in treated mice and the availability of DCs that can cross-present the tumor antigens released by radiation is critical." (PMID 25349699, 2014). "Therefore, data indicate that iNKT cells regulate DC numbers in 4T1 tumor-bearing WT mice via CD1d-mediated interactions." (PMID 25349699, 2014). "We hypothesized that the interaction of iNKT cells with CD1d+ APC could modulate the ability of WT mice to develop anti-tumor immune responses upon treatment." (PMID 25349699, 2014). "Accordingly, the authors suggested that tumor expression of CD1d might shift the NKT cell response toward a Th2 skewed anti-inflammatory reaction, which produces more IL-13, TGF-β, and inhibition of CTL and NK cell activity." (PMID 25389427, 2014). "In addition, immunity against a number of tumor models has been observed with the therapeutic activation of NKT by selective agonist α-galactosylceramide presented by CD1d+ APCs." (PMID 25009659, 2014). "CD1d-restricted T-cell populations have a physiological role in tumor immunosurveillance, which is mediated at least partly through the maturation of antigen-presenting cells (APCs; including monocytes, macrophages and dendritic cells) and IL-12 induction via NK and CD8+ T cells." (PMID 25009659, 2014). "Next, we investigated whether the improved anti-tumor T cell response seen in the presence of CD1d blocking mAb results in improved tumor response to treatment." (PMID 25349699, 2014). "To determine if blockade of CD1d resulted in improved priming of anti-tumor CD8+ T cells in dLN of WT mice treated with local radiotherapy and anti-CTLA-4 mAb, we measured tumor antigen-specific production of IFNγ by dLN cells stimulated with a CD8 T cell epitope derived from the tumor antigen gp70." (PMID 25349699, 2014). "The reduction at end stage was significant (n = 6) In naive mice, CD1d was less expressed on BM cells compared to spleen cells (52%±2.1) and in tumor bearing mice, the expression declined in week 1 and week 2 (35%±7.2 and 43%±1.6 respectively) but did not decline further at the terminal point." (PMID 23741460, 2013). "Rather than a drawback, the lower potency of soluble monomeric CD1d molecules will be rather favorable in limiting a potentially detrimental systemic activation of iNKT cells, while promoting their sustained activation when targeted at the tumor site." (PMID 23242316, 2013). "Finally, the efficient tumor targeting of CD1d molecules requires the over-expression of a tumor antigen for which a high-affinity antibody scFv has been developed." (PMID 23242316, 2013). "One is to establish artificial adjuvant vector cells containing tumor mRNA and α-GalCer/CD1d." (PMID 24348476, 2013). "Therefore, the targeting of CD1d molecules to the tumor site not only triggers iNKT-mediated tumor lysis, but also favors local innate and adaptive antitumor responses, as suggested by the accumulation of iNKT, NK, and T cells at the tumor site." (PMID 23242316, 2013). "Some tumor cells such as lymphomas and leukemias also express CD1d molecules on their surface." (PMID 24009709, 2013). "In view of the rare expression of CD1d on tumor cells, the direct cytotoxicity of iNKT cells against tumors has been disregarded, and instead, the immediate antitumor activity of iNKT cells was shown to be largely mediated by the transactivation of natural killer cells." (PMID 23242316, 2013). "Strategies to block the regulatory functions of iNKT cells, or interfere with their tumor-mediated conditioning, for example by blocking CD1d, could be beneficial to improve the effects of immunotherapy and other treatments." (PMID 23118781, 2012). "Unlike previous studies using antibody blockade of CD1d-deficient tumors, treatment of CD1d-expressing TM40D cells with anti-CD1d blocking antibody did not inhibit tumor growth." (PMID 21695190, 2011).
tumor (continued). "In late-stage metastatic breast cancer, such as in TM40D-MB, presentation of inflammatory tumor antigens by even a low level of CD1d may be sufficient to drive type II NKT-mediated immune suppression." (PMID 21695190, 2011). "TM40D (CD1d-hi) tumor cells demonstrated increased cytotoxicity over TM40D-MB (CD1d-lo) tumor cells in a range of effector to target cell ratios, and significantly higher cytotoxicity at an E:T ratio of 25∶1 (P<0.05), as measured by the release of lactate dehydrogenase (LDH)." (PMID 21695190, 2011). "Splenocytes isolated from the TM40D (CD1d-hi) group demonstrated lower levels of NK and iNKT cells as compared to healthy unchallenged mice, as expected from immune suppression at this late stage of tumor progression." (PMID 21695190, 2011). "Activated iNKT cells have been demonstrated to be directly cytotoxic to CD1d-bearing tumor cells in a CD1d-dependent manner in vitro, and studies have directly correlated tumor expression of CD1d to their sensitivity to iNKT-mediated antitumor immunity in vivo." (PMID 21695190, 2011). "In addition, these results point to the CD1d expression status of the tumor as being an important determinant in tailoring NKT-based immunotherapies for the prevention and treatment of metastatic breast cancer." (PMID 21695190, 2011). "Importantly, splenic levels of NK and iNKT cells of the TM40D mice were significantly higher than in the TM40D-MB (CD1d-lo) group (NK and iNKT P<0.001), although tumor sizes were comparable at time of analysis." (PMID 21695190, 2011). "This supports the notion that downregulation of tumor CD1d expression may play a role in suppressing the antitumor immune functions of iNKT cells." (PMID 21695190, 2011). "Whether (CD1d+) tumor cells present type-II NKT–stimulating ligands remains an unsolved, challenging question." (PMID 24212972, 2011). "Rather, the ability of CD1d-expressing tumor cells to promote type I over type II NKT immune responses may depend more on the type of tumor antigen presented by CD1d molecules." (PMID 21695190, 2011). "In addition to their indirect antitumor immune functions, multiple studies confirm the ability of iNKTs to be directly cytotoxic to tumor cells in a CD1d-dependent manner." (PMID 21695190, 2011). "This suggests that downregulation of tumor CD1d expression may have an effect on NK and iNKT antitumor immunity, even at a late stage in tumor progression." (PMID 21695190, 2011). "Recent studies have begun to elucidate a novel immunoregulatory axis of CD1d-restricted NKT cells, with type I invariant NKT (iNKT) having antitumor functions, and type II variant NKT cells demonstrating mainly immunosuppressive tumor-promoting abilities." (PMID 21695190, 2011). "Recent studies indicate that tumor cells expressing CD1d may present lipid antigens thereby bias the effector functions of type-I NKT cells towards tolerance." (PMID 24212972, 2011). "In accordance with this NK-like phenotype and as previously reported, CD8α+ and DN iNKT cells displayed more potent cytotoxicity than CD4+ iNKT cells against a number of CD1d+ tumor cell lines, with consistently higher proportions expressing cell-surface CD107a and killing target cells." (PMID 22174854, 2011). "This suggests that enriched iNKT cells may preferentially target tumor cells expressing higher levels of CD1d, and downregulation of CD1d may be a mechanism for evading direct iNKT-mediated cytotoxicity." (PMID 21695190, 2011). "Flow cytometry data were supported by costaining of tumor sections for CD1d and CD4 or NK.1.1." (PMID 21779410, 2011). "This suggests that while CD1d expression in these tumor cells is downregulated, they may still be capable of being recognized by type II NKT cells." (PMID 21695190, 2011). "In order to assess the effect of CD1d antibody blocking on tumor metastasis, we evaluated whether anti-CD1d antibody blockade could increase tumor metastasis to lung." (PMID 21695190, 2011).